PCSK9 (proprotein convertase subtilisin/kexin type 9)
Diseases named in the same sentence as PCSK9 in open-access papers (continued):
Sharing a sentence is not in itself a finding about the gene and the disease.
infection (35 papers, 2012 to 2026). The state of being infected such as from the introduction of a foreign agent such as serum, vaccine, antigenic substance or organism. "In addition, infection of C57BL/6 mice with AAV that obtained stable expression of functionally mutated mouse PCSK9 provided a model for rapid enhancement of AngII-induced AAA8." (PMID 37055467, 2023). "Some studies suggest that higher cholesterol and/or PCSK9 function are associated with better response to some infections while others reported lower risk and/or better outcomes with lower PCSK9 and/or LDL-C. It is important to consider the distinctions of these studies." (PMID 30726226, 2019). "Assuming the validity of the prior studies, our current results suggest that a PCSK9 inhibitor may increase infection risk through mechanisms other than downregulation of hepatic LDL-Rs." (PMID 30726226, 2019). "In mice, endotoxin elevates plasma PCSK9 levels and plasma PCSK9 levels might be similarly elevated in humans after an acute infection and contribute to increased risk of subsequent MI." (PMID 25180781, 2014). "Of patients with infection, genotype information was available in 10 922 white patients for PCSK9 functional variants (5628 men [51.5%]; mean [SD] age, 60.1 [15.7] years), including 7624 patients with PCSK9 GRS and 6033 patients with estimated PCSK9 expression." (PMID 31509211, 2019). "An important related question is whether PCSK9 inhibitors may influence infection risk." (PMID 30726226, 2019). "A similar result was observed in PAMs; endogenous PCSK9 expression decreased as the infection time increased, whereas that of the PRRSV N protein did the opposite." (PMID 32560445, 2020). "G2 infection appeared to be more effective in inducing PCSK9, and significantly lower levels were observed in the G3 phenotype." (PMID 32998342, 2020). "The WB result showed that the PCSK9 protein level decreased as the infection time increased compared to that in the mock infection control." (PMID 32560445, 2020). "The LS-MS/MS result showed that the PCSK9 expression level increased significantly upon PRRSV strain HuN4-eGFP infection in PAMs compared to in the mock infected PAMs." (PMID 32560445, 2020). "Previously published data reporting elevations of PCSK9 in infection have mostly derived from animal models and, in a clinical setting without a direct control cohort within the study, among septic patients upon presentation at the emergency department." (PMID 31843964, 2020). "To further define the role that PCSK9 plays in DENV infection, we supplemented Huh7 cell cultures with recombinant PCSK9 before infection." (PMID 32644974, 2020). "Therefore, we examined the antiviral activity of these mutated PCSK9 proteins by overexpressing these mutants in MARC-145 cells, followed by PRRSV strain HuN4 infection." (PMID 32560445, 2020). "The PCSK9 expression level decreased as the time increased after infection." (PMID 32560445, 2020). "Similarly, PCSK9 LOF variants were associated with an increased clearance of pathogen lipids, a decreased 1-year mortality, and recurrent infection in septic survivors." (PMID 33123601, 2020). "Moreover, LDL levels were reported to be decreased in critically ill patients and severe infections, although elevated levels of PCSK9 should, in theory, increase levels of LDL cholesterol." (PMID 31843964, 2020). "Finally, the mutual interaction between HCV and PCSK9 is supported by the fact that its promoter activity is induced in response to infection and that PCSK9 inhibits HCV replication." (PMID 32998342, 2020).
infection (continued). "However, knowledge about the role and kinetics of PCSK9 in human inflammation and, importantly, the potential benefits of its pharmacological inhibition in infection is still scarce." (PMID 31843964, 2020). "Serious infection hospitalizations occurred in 779 participants (14 with PCSK9 variants and 765 without)." (PMID 30726226, 2019). "Infection and inflammation play a key role in the expression of PCSK9 in mice model." (PMID 29770231, 2018). "PCSK9 inhibitors did not increase acute rejection or infection risk in SOT recipients." (PMID 40918505, 2025). "Furthermore, to determine which domain of PCSK9 protein is crucial for the antiviral activity, we constructed several PCSK9 variants with peptides truncated then overexpressed these truncated PCSK9 proteins in MARC-145 cells, followed by PRRSV strain HuN4 infection." (PMID 32560445, 2020). "Because much of the detail of PCSK9’s function beyond LDL-R downregulation is yet unknown, additional studies are needed to clarify the pathways of PCSK9 inhibitors and their effects on infection risk." (PMID 30726226, 2019). "Therefore, other mechanisms may regulate Pcsk9 expression during infection; further studies will be needed to answer this question." (PMID 22992388, 2012). "However, it remains to be elucidated how infection affects PCSK9 protein secretion." (PMID 22992388, 2012). "In patients with poor outcome and infection, PSME1, MTREX, and H2B1C were more abundant in T cell-derived EVs; COHA1 was less abundant in B cell-derived EVs; and PCSK9 and CMC1 were less abundant in the monocyte-derived EVs." (PMID 41345658, 2025). "Additionally, the safety profile of PCSK9 inhibitors was explored, with particular attention given to potential adverse reactions in specific patient groups, such as injection site reactions, infections, or changes in the incidence of neurocognitive events (NCEs)." (PMID 40918505, 2025). "We first performed lentivirus infection in Huh7 and PLC/PRF/5 cells for the knockdown of PCSK9, whereas performed overexpression of PCSK9 in cell lines Li7 and MHCC-97H with relative low expression of PCSK9 according to their expression in HCC cell lines." (PMID 37151886, 2023). "E2F1 inhibits the clearance of circulating cholesterol by regulating the expression of PCSK9, which might be related to the parasite’s critical need of cholesterol-related metabolism from Boran’s body, implicating the progressive conditions of hypocholesteraemia and hypolipidaemia after infection." (PMID 33429951, 2021). "The level of the epigenetic marker at the position of genes WNT10A, JUNB, FOSL2, TNFAIP3, KLF4 and EDN1 was increased, and decreased at the position of genes MYCN and PCSK9, as was demonstrated by using the in vitro HCV-infection systems." (PMID 31216276, 2019). "PCSK9 inhibitors effectively reduced LDL-C in transplant recipients without increasing acute rejection or infection risks, supporting their use in this population." (PMID 40918505, 2025).
infection (continued). "Meanwhile, the PLEASe Study (NCT03869073), Treatment of Severe Infection With Antihyperlipidemia Drug (NCT03634293), and PALMS (NCT05469347), are aiming to ascertain if quick bacterial component removal via PCSK9 neutralization with Evolocumab or Alirocumab proves beneficial." (PMID 38185721, 2024). "PCSK9 expression increased in the early stage of PRRSV infection, but the increase was suppressed in the late stages of infection, suggesting that proteins produced during PRRSV replication could negatively regulate PCSK9 expression." (PMID 32560445, 2020). "While our data suggest that there are mechanisms raising LDL plasma concentrations in the very early phase of infections and that this rise correlates with the degree of inflammation, this effect of LDL recovery in inflammation is entirely independent of PCSK9." (PMID 31843964, 2020).
metabolic disorders (28 papers, 2016 to 2026). "PCSK9 is associated with endothelial cell apoptosis, macrophage cholesterol efflux, intracellular mitochondrial dysfunction, and inflammation, all of which lead to metabolic disorders." (PMID 38115042, 2023). "Among the most fascinating applications of CRISPR in metabolic disorders is editing PCSK9 (Proprotein Convertase Subtilisin/Kexin Type 9), a basic regulator of cholesterol metabolism." (PMID 40430848, 2025). "PCSK9 drugs, such as PCSK9 antibodies and siRNA therapies, are novel therapeutics for metabolic diseases." (PMID 40006605, 2025). "Given the roles of such proteins in the context of CVD and other metabolic disorders, the long-term effects of therapies that block de novo synthesis of PCSK9 protein remain to be elucidated." (PMID 35323658, 2022). "First, the use of a single baseline PCSK9 measurement to predict outcomes was a simplified and practical approach but was unable to assess the relationship between changes in PCSK9 levels and the incidence of metabolic disorders." (PMID 34041285, 2021). "Considering the importance of 2-hPG in CVD and the crucial role of PCSK9 in the development of CVD, we therefore aimed to investigate the association of PCSK9 and 2-hPG in metabolic diseases in a Chinese Han population." (PMID 29343301, 2018). "Although cilostazol treatment exerted a beneficial effect on some metabolic disorders and vasculo-angiogenic biomarkers, the increase in PCSK9 concentrations with this drug were probably mediated through other mechanisms." (PMID 29296222, 2017). "Drugs that regulate metabolic diseases by targeting PCSK9 have recently drawn great attention all over the world." (PMID 26833058, 2016). "Considering the important role of proprotein convertase subtilisin/kexin type 9 (PCSK9) in metabolic diseases, we explore the possible mechanism of polydatin on lipid and glucose metabolism through its effects on PCSK9." (PMID 26833058, 2016). "Breakthroughs in these areas may be attributed to the maturation of liver-targeted delivery systems (e.g., GalNAc coupling technology), which have made metabolic disorders (e.g., PCSK9 targeting) more amenable to efficient gene silencing." (PMID 41041638, 2025). "Obese subjects have higher PCSK9 levels than lean controls, suggesting that PCSK9-targeting therapy may be important in such metabolic disorders." (PMID 36077166, 2022). "In addition, lipoprotein disorders in which LDL-C concentrations are genetically reduced have been reported, and among them, patients with mutations in the ANGPTL3 and PCSK9 genes are asymptomatic." (PMID 33255270, 2020). "Serum PCSK9 levels positively correlated with 2-hPG in patients with metabolic diseases." (PMID 29343301, 2018). "In considering the effects of cilostazol treatment on some metabolic disorders, vasculo-angiogenic biomarkers, and PCSK9 concentrations, cilostazol use might have a prognostic impact in patients with PAD or at a high risk of CVD." (PMID 29296222, 2017). "As proof, subcutaneous injection of the PCSK9 inhibitor SBC-115076 had greater benefit than the cholesterol-reducing drug atorvastatin in improving metabolic disorders of obese rats, because, according to the authors, it could decrease PCSK9 activity in the intestine and cholesterol absorption." (PMID 39769398, 2024).
metabolic disorders (continued). "Based on the traditional uses of this plant for different ailments, metabolic diseases and cardiovascular problems we have explored the effects of the main constituents on the LDL and PCSK9 targets." (PMID 35408655, 2022). "The clinical consequences of renal PCSK9 fluctuation so far have not been assessed, mainly because of multiple interconnection and indirect feedback with a plethora of factors involved in inflammatory and metabolic disorders." (PMID 34576046, 2021). "Thus, we conclude that 1) elevated serum PCSK9 concentration could be a early biomarker for T2DM independent of other metabolic parameters; and 2) serum PCSK9 levels and 2-hPG are positively correlated in patients with metabolic diseases." (PMID 29343301, 2018). "We explored the relationship between circulating PCSK9 levels and CETP activity in patients with metabolic disease who were not on lipid-lowering therapy." (PMID 27488210, 2016).
genetic disorder (15 papers, 2016 to 2026). "There are also reports on genetic disorders, for example, mutations in the Proprotein convertase subtilisin/kexin 9 (PCSK9) gene, in connection with the study of lipoprotein metabolism kinetics." (PMID 41596209, 2026).
heart disease (14 papers, 2016 to 2025). "It has long been recognized that reduced PCSK9 activity leads to decreased serum cholesterol levels and to decreased risk of heart disease." (PMID 34451861, 2021). "So, for example, loss-of-function mutations of PCSK9 lead to dramatically decreased circulating cholesterol and reduced risk of heart disease." (PMID 34451861, 2021). "The decrease in Apo-B/Apo-A1 ratio obviously indicates that PCSK9-mAb therapy greatly lowers the primary risk factors of heart disease." (PMID 28331223, 2017). "PCSK9 inhibitors also impact Lipoprotein(a) [Lp(a)], a lipoprotein linked to heart disease." (PMID 39770423, 2024). "Inactivation of Pcsk9 appeared to reduce cholesterol levels and the risk of heart disease." (PMID 38426160, 2024). "Furthermore, recent studies have revealed the possible associations between heart disease and PCSK9 independently from the cholesterol regulations." (PMID 35323699, 2022). "Completed and any phase clinical trials that were registered in the Clinicaltrials.gov database using PCSK-9 inhibitors as major intervention and related to heart diseases until January 19th, 2024 were included in this review." (PMID 39252316, 2024). "A review was conducted of all clinical trials with PCSK-9 inhibitors for heart diseases registered at ClinicalTrials.gov since inception up to and including January 19th, 2024." (PMID 39252316, 2024). "Of the 3363 black subjects examined, 2.6% had nonsense mutations in PCSK9; these mutations were associated with a 28% reduction in mean LDL cholesterol and a significant 88% reduction in the risk of ischaemic heart disease." (PMID 33919478, 2021). "Of the 9524 white subjects examined, 3.2% had a sequence variation in PCSK9 that was associated with a 15% reduction in LDL cholesterol and a significant 47% reduction in the risk of ischaemic heart disease." (PMID 33919478, 2021). "This review identified only a few clinical trials on PCSK-9 inhibitors in heart disease patients." (PMID 39252316, 2024). "PCSK-9 inhibitors represent a promising class of lipid-lowering medications that have demonstrated a significant reduction in LDL-C levels and a decreased risk of major cardiovascular events in patients with heart disease." (PMID 39252316, 2024). "PCSK9 influences heart disease progression through multiple pathways, such as LDL receptor downregulation, which increases LDL levels, inflammation through engagement with Toll-like receptors (TLRs), and clot formation by interacting with platelet glycoprotein IV (CD36) to activate platelets." (PMID 39770423, 2024). "The ASPirin in Reducing Events in the Elderly trial also demonstrated that PCSK9 pR434W is a member of lipid-lowering PCSK9 and APOB genetic variants that are carried by healthy older individuals (aged ≥ 70 years) and contribute to coronary-heart-disease-free survival." (PMID 36142332, 2022). "Earlier research mainly focused on PCSK9′s effect on cholesterol, while recent advancements include gene editing techniques like CRISPR and new treatments for heart diseases, advancing future research in heart health and PCSK9." (PMID 39770423, 2024).
kidney disease (12 papers, 2020 to 2025). "The role of proprotein convertase subtilisin/kexin type-9 (PCSK9) in renal disease is an area that has garnered increasing attention." (PMID 40289090, 2025). "Despite significant reductions in LDL-C with PCSK9 inhibitors, there is clinical trials on their effects on kidney diseases." (PMID 40289090, 2025). "This included well-described examples, such as UMOD and kidney disease or established drug targets like PCSK9 and LDL-cholesterol." (PMID 36823471, 2023). "On the other hand, in an adriamycin-induced nephropathy model, renal expression of PCSK9 decreased as well as that of its transcriptional activator HNF-1α, whereas that of LDL-Rs increased and lipid deposition in renal cells was favored." (PMID 33364976, 2020). "Studies have found contradictory relationships between PCSK9 levels and kidney disease." (PMID 38510702, 2024). "Drugs targeting PCSK9 directly (such as the FDA-approved monoclonal antibody evolocumab) or affecting its expression (such as Ginkgolide B) have been shown to be effective in the case of kidney diseases." (PMID 37242602, 2023). "PCSK9 levels are not correlated with the severity of kidney disease." (PMID 34336112, 2021). "However, the mechanism by which PCSK9 inhibition might exert its protective effect in kidney disease is not well elucidated." (PMID 37242602, 2023).
infectious disease (11 papers, 2020 to 2026). A disorder directly resulting from the presence and activity of a microbial, viral, or parasitic agent in humans. "This study focuses on a genetic factor, i.e., the rs562556 SNP of the PCSK9 gene, in light of the mounting evidence indicating that the activity of the encoded protein influences immunity in infectious diseases." (PMID 33029265, 2020). "Previous studies have revealed a possible correlation between PCSK9 and the development of infectious diseases, and PCSK9 is expected to be a therapeutic target." (PMID 39736777, 2024). "Given the ability of PCSK9 to bind LDL-R and modulate LDL clearance from plasma, PCSK9 was hypothesized to play a role in infectious diseases and inflammation." (PMID 35162992, 2022).